MBD3L1 (methyl-CpG binding domain protein 3 like 1)
Description:
Transcriptional repressor.
Synonyms: MBD3L
Tractability: No criterion of Open Targets' tractability assessment is met for any kind of drug.
Gene: Protein-coding gene on chromosome 19 (8,832,377 to 8,843,340, forward strand). Ensembl gene ENSG00000170948.
Subcellular location: Nucleus
Pathways (Reactome):
Chromatin organization: NuRD complex assembly
Gene Ontology:
Molecular function: protein binding; methyl-CpG binding
Biological process: DNA methylation-dependent constitutive heterochromatin formation; negative regulation of transcription by RNA polymerase II
Cellular component: nucleoplasm; nucleus
Genetic constraint (gnomAD): Loss-of-function variants: 0 observed, 0.0826 expected, observed/expected ratio (o/e) 0, 90% interval 0 to 1.89. That is too few expected variants to judge how well the gene tolerates losing a copy. Missense variants: 200 observed, 234.86 expected, observed/expected ratio (o/e) 0.85, 90% interval 0.76 to 0.96. Synonymous variants: 83 observed, 87.96 expected, observed/expected ratio (o/e) 0.94, 90% interval 0.79 to 1.13.
Homologues: Orthologues: chimpanzee MBD3L1 (97% identical), macaque MBD3L1 (92% identical), dog MBD3L1 (65% identical), mouse Mbd3l1 (59% identical), rat Mbd3l1 (58% identical), zebrafish mbd3a (43% identical), tropical clawed frog mbd3 (42% identical), Drosophila melanogaster MBD-like (22% identical). Paralogues in human: MBD3 (45% identical), MBD2 (40% identical), MBD3L2 (38% identical), MBD3L2B (38% identical), MBD3L3 (38% identical), MBD3L4 (38% identical), MBD3L5 (38% identical), MBD1 (23% identical).
Diseases named in the same sentence as MBD3L1 in open-access papers:
MBD3L1 is named in the same sentence as 1 disease in open-access papers, as found by Europe PMC text mining. Sharing a sentence is not in itself a finding about the gene and the disease.
MBD3L1 shares sentences with these, for which no sentence is quoted: psoriasis (1 paper).